ERG (ETS transcription factor ERG)
Diseases named in the same sentence as ERG in open-access papers (continued):
Sharing a sentence is not in itself a finding about the gene and the disease.
tumor (continued). "However, the role of miR-196b in leukemia is still controversial, as it is involved also in the regulation of oncoproteins such as ERG and c-myc, suggesting a tumor suppressive activity." (PMID 33247705, 2020). "Expression of vascular markers CD31, CD34 and ERG confirmed endothelial lineage of the tumor cells." (PMID 32977811, 2020). "In conclusion, we revealed tumor suppressive abilities of miR-223-5p in PCa by targeting ERG gene." (PMID 32489464, 2020). "The relationship between CD138 expression and 11 of the most frequent genomic deletions (PTEN, 3p13, 5q21, 6q15, 13q14, 18q21, 8p21, 12p13, 12q24, 16q24, 17p13) was not only analyzed for the entire tumor cohort but also for the subgroups with identical ERG status." (PMID 33195694, 2020). "Moreover, western blotting indicated reduced levels of ERG protein in E43′ SSO-treated tumours versus untreated and control tumours, suggesting incorporation of the SSOs into tumours." (PMID 32581342, 2020). "Subset analyses in 2725 cancers with and 3592 cancers without TMPRSS2:ERG fusion revealed that associations with tumor phenotype and patient outcome were largely driven by the subset of ERG negative tumors." (PMID 32677026, 2020). "Considering the multiclonal and heterogenous nature of CaP, it is important to examine all tumor foci for ERG fusion status as any of these may lead to aggressive CaP." (PMID 32341752, 2020). "The complete lack of a prognostic value of hnRNPA1 in ERG-positive cancers, however, might suggest that ERG activation overrides the tumor-promoting function of hnRNPA1." (PMID 32417965, 2020). "They showed that local control after MDT was associated to non-organ confined tumor category, low Gleason index, stromal reaction, mild inflammation, atrophy, Ki67 > 5% and ≥ 5%, ERG, PGP 9.5, CRG, and SYN immunostainings." (PMID 33291528, 2020). "We obtained multiple cores from the tumours of five patients; however, we could only detect ERG expression in one of the samples designated PPL-0209." (PMID 32581342, 2020). "Moreover, EC-8042 had a significant impact of the CSC subpopulation in ERG/PTEN mice as indicated by reduced ex vivo tumor-sphere formation and CSC marker expression." (PMID 31143708, 2019). "This study, therefore, confirms that ERG could play an essential role in tumor angiogenesis and growth and that downregulation of ERG expression could be an effective strategy towards developing new anticancer therapies." (PMID 31817884, 2019). "Moreover, the ERG/PTEN derived tumor-spheroids were endowed of high in vitro self-renewal potential and were capable of generating tumors with high efficiency when re-implanted in mice." (PMID 31143708, 2019). "TAK1 deletion was associated in both ERG-rearranged and not ERG-rearranged groups with early tumor recurrence." (PMID 31366128, 2019). "A number of studies from experimental models suggest a basal cell origin: thus, experiments of transformation with lentivirus containing ERG and androgen receptor genes of sorted luminal and basal cells provided evidence that only the latter ones displayed tumor formation." (PMID 31366128, 2019). "Subset analyses in 5,415 cancers with and 4,217 cancers without TMPRSS2:ERG fusion revealed that these associations with tumor phenotype and patient outcome were largely driven by the subset of ERG-negative tumors." (PMID 31903168, 2019). "Based on the finding of a relevant fraction of ERG/Sp1 co-regulated genes among the ERG activated targets in ERG-fusion positive tumor, we tested the activity of a novel DNA binding and Sp1 interfering compound, demycarosyl-3D-β-D-digitoxosyl-mithramycin SK (EC-8042), in ERG positive models." (PMID 31143708, 2019). "Furthermore, using an ERG-positive PDX model we demonstrated that sGC inhibitor treatment was also effective in reducing tumor growth of CRPC." (PMID 30718921, 2019).
tumor (continued). "Analysis of ERRα and ERG expressions in VCaP-CRPC tumor biopsies revealed that mRNA and proteins levels of both ERRα and ERG declined at fourth day postcastration but their levels rebounded significantly in castration-relapse xenograft tumors at levels higher than precastration." (PMID 30042415, 2018). "These indications are associated with increased tumor angiogenesis and lack of ets-related gene (ERG) expression which leads to reduced vitamin D and androgen receptor expression." (PMID 30622933, 2018). "Our focuse on the ERG-negative group could provide a reference for populations with low frequency of ERG positive tumor types." (PMID 30150711, 2018). "Thus,ERG overexpression is a weak driver of tumor development in mice, but it can accelerate tumor development in the context ofPten downregulation." (PMID 30135717, 2018). "ERG has also been reported to positively regulateMYC115,118 andNOTCH119, both of which are key for prostate differentiation and tumor development, suggesting thatERG may have a role in disrupting terminal differentiation." (PMID 30135717, 2018). "Verteporfin treatment decreases VCaP (ERG+) xenograft tumor growth in mice." (PMID 30135717, 2018). "This study found that ERG was positive in the dominant tumor nodule in 22% of cases." (PMID 28186998, 2017). "ERCC1 staining was similarly linked to unfavorable tumor phenotype in subsets of both ERG-negative and ERG-positive cancers." (PMID 28747165, 2017). "FAM13C immunostaining was similarly linked to unfavorable tumor features in subsets of both ERG negative and ERG positive cancers." (PMID 28415558, 2017). "In CTCs harboring ERG-rearrangement, tumor heterogeneity was assessed by ERG-copy number." (PMID 27391263, 2016). "It is likely that multiple factors may contribute to our observations, including level of ERG expression in primary tumors, immune surveillance of the host, tumor heterogeneity, MHC background and antigen presentation." (PMID 28191285, 2016). "All 1592 tumor-containing sections were analyzed by immunohistochemistry for ERG expression." (PMID 27530104, 2016). "Since it has been suggested that tumor antigens are released from cells either actively or through lysis of tumor cells, we considered the possibility that ERG protein may also be present in patient sera." (PMID 28191285, 2016). "We observed over-expression of ERG in tumor samples compared to normal samples." (PMID 28027300, 2016). "RNAseq analyses in both centers identified fusion transcripts including a common rearrangement between TMPRSS2 and ERG in one tumor, though the detection of other fusion transcripts varied substantially depending on the algorithm used to identify such transcripts." (PMID 27167109, 2016). "Moreover, in two patients harboring ERG-rearrangement in CTCs, tumor heterogeneity seems to be significantly higher in CTCs compared to paired primary tumors and metastasis biopsies (P<0.0001)." (PMID 27391263, 2016). "It is becoming increasingly clear that ERG+ and ERG− PCs represent distinct molecular subtypes and that subtype-specific markers may be required for prediction of tumor aggressiveness." (PMID 26478752, 2015). "It is therefore possible that these molecules might negatively affect ERG+PCa if they are present in the tumor microenvironment." (PMID 26310325, 2015). "Interestingly, ERG itself represents a potential therapeutic target in tumours with ERG rearrangements." (PMID 25896606, 2015). "Finally, our model suggests that in tumour cells harbouring an ERG gene fusion iii) AR activation of the ERG fusion gene creates a dynamic negative feedback loop impacting on both the AR and HES6, creating a more complex transcriptional network." (PMID 25560400, 2015). "SENP1 immunostaining was similarly linked to unfavorable tumor features in subsets of both ERG negative and ERG positive cancers." (PMID 26202067, 2015). "Within the tumours, a strong inhibition of ERG oncoprotein was detected." (PMID 25933120, 2015).
tumor (continued). "Nuclear tumor ERG staining was observed in 34% of the patients." (PMID 24505269, 2014). "Discrepancies in the reported prognostic significance of ERG rearrangements can be due to cohort design (multifocality and zonal origin of the tumor), fusion detection technique, and are also liable to the primary end point of the study (i.e., biochemical recurrence, overall survival)." (PMID 24516518, 2014). "Notably there are also changes in the tumor stroma related to tumor aggressiveness (for example decreased androgen receptor expression and mast cell numbers) that are apparently unrelated to epithelial ERG status." (PMID 24505269, 2014). "In ERG fusion-positive cancers, the fraction of tumors with p27 loss was low and unrelated to the Gleason grade, suggesting that neither tumor differentiation nor progression are dependent on p27 levels." (PMID 24179503, 2013). "Mouse prostates devoid of PTEN display enhanced tumor genesis in the presence of overexpressed ERG." (PMID 23565244, 2013). "Different genomic rearrangements and alternative splicing events around the junction region lead to multiple combination of Tmprss2:ERG fusion transcripts that correlate with different tumor aggressiveness, but their specific functions and biological activities are still unclear." (PMID 23472063, 2013). "CA men were also significantly more likely to have any tumor focus positive for ERG (59% vs. 41%)." (PMID 23892597, 2013). "Nevertheless, in one case, TMPRSS2/ERG-expressing tumor metastasized into the murine lung." (PMID 21747944, 2011). "Functional annotation analysis of the transcriptome of ERGhigh and ESE3low tumors linked both ERG and ESE3 to critical processes in tumor initiation and progression and suggested that their deregulation might induce partially overlapping features." (PMID 20479932, 2010). "ERG was bound to the Nkx3.1 promoter in ERGhigh tumors, consistent with the hypothesis that it controlled negatively transcription of the gene in this tumor subgroup." (PMID 20479932, 2010). "Finally, to prove that this interaction occurred also in clinical tumor specimens we performed ChIP to assess binding of ERG to the EZH2 promoter in ERGhigh and NoETS samples." (PMID 20479932, 2010). "As previously reported, patients with TMPRSS2–ERG fusion-positive tumours had a significantly higher expression of ERG transcripts (P-value 3.48 × 10−11, two-sided Student's t-test), which is most likely a result of androgen-responsive promoter elements in TMPRSS2 driving expression." (PMID 20068566, 2010). "Interestingly enough, the aggressive tumor behavior, i.e., metastatic disease, was associated with a copy number increase of TMPRSS2:ERG loci on chromosome 21." (PMID 24281166, 2010). "Our results are similar in that those tumours that had neither an ERG gene rearrangement nor PTEN loss were in a good prognostic group." (PMID 20104229, 2010). "On these bases, we identified three major tumor subgroups characterized by the predominant dysregulation of an ETS factor: i) tumors with high ERG expression (ERGhigh, n = 14), ii) tumors with high ESE-1 expression (ESE1high, n = 12) and iii) tumors with low ESE3 expression (ESE3low, n = 13)." (PMID 20479932, 2010). "Attard and colleagues (2007) suggest that the sequence intervening the TMPRSS2 and ERG genes may contain tumor-suppressor genes which when lost, increase disease aggressiveness." (PMID 18694509, 2008). "Among the 81 patients who had TMPRSS2:ERG fusion transcripts within their tumour tissue, 37 (45.7%) experienced biochemical recurrence, whereas among the 84 patients who had tumours that lacked fusion, only six (7.1%) experienced a relapse (odds ratio=10.9, 95% CI=4.3–27.9, P=10−7)." (PMID 17971772, 2007).
tumor (continued). "Emerging therapeutic strategies, such as precision medicine approaches that target vulnerabilities in ERG driven pathways and DNA repair mechanisms, such as PARP inhibitors, may benefit a subset of these tumours, particularly those with additional mutations in DNA damage repair genes." (PMID 40165885, 2025). "In clinically established metastases, we showed that most tumor cells were clustered around small blood vessels (ERG+, SDF1+, POSTN+, SMA+, PDGFRB+), suggesting that other cell interactions, especially involving blood vessels, might drive later stages of metastasis growth." (PMID 40841830, 2025). "Immune checkpoint inhibitors also represent a potential therapeutic avenue for ERG+/PTEN+ tumours, as this subtype may maintain a more immunologically active tumour microenvironment compared to PTEN-deficient subtypes, though the efficacy of these treatments remains under research." (PMID 40165885, 2025). "Our aim was to analyze the protein expression of PTEN, SPOP, SLC45A3, ETV1, ERG and the “triple hit” (ERG overexpression, PTEN plus SLC45A3 loss) in unifocal (UF) and MF PCa, to evaluate their value as prognostic markers according to focality, and the role of tumor heterogeneity in MF disease." (PMID 38017230, 2024). "Starting from normal or a branch that contained a mixture of ERG fusion–positive and –negative samples, both models displayed a linear, bifurcating progression pattern with two major branches associated almost exclusively with ERG fusion–positive or –negative tumor samples." (PMID 39347576, 2024). "To identify tumor-related immune cells and whether specific immune cell types were differentially enriched in either ERG + or ERG− samples, we analyzed the T-cell population and identified CD4 and CD8 T-cells, regulatory T-cells (Treg), and NK cells based on differentially expressed genes." (PMID 35013146, 2022). "Therefore, the tumor’s reliance on AR signaling may also dictate the role that ERG plays during disease progression." (PMID 36212399, 2022). "Controversies have emerged as to whether ERG activates or attenuates the AR signaling, leading to the hypothesis that ERG can promote the oncogenic functions of AR (e.g., promoting survival of the prostate cells) while inhibiting the tumor-suppressing ones (e.g., differentiation)." (PMID 35267426, 2022). "Since, the genetic background of the tumor may dictate how ERG influences AR activity we propose that the results from patient cohorts may be obfuscated by mixed genetic backgrounds of patient tumor samples." (PMID 36212399, 2022). "Furthermore, we compared the numbers of ERG+ tumor cell and ERG− tumor cells in each patient." (PMID 35013146, 2022). "Interestingly, the association of high JUP expression with adverse tumor features was mainly observed in ERG fusion‐negative patients." (PMID 33533127, 2021). "Irrespective of its cause, the different prognostic impact of SNW1 in ERG positive and ERG negative cancers demonstrates that the applicability (and perhaps thresholds) of prognostic markers may depend on individual tumor features." (PMID 31043167, 2019). "It is notable that the post-AI ESR1-mutated tumour with the lowest oestrogen-regulated expression carried an E380Q mutation and was also HER2-positive though this is the only ESR1-mutated sample with HER2 overexpression making the importance of its association with low ERG expression uncertain." (PMID 30563991, 2019). "Heretofore WNT/β-catenin signaling has been implicated in PCa tumor cell self-renewal, pathogenesis, and aggressive disease, and activated WNT/β-catenin signaling has been described to be among the most highly enriched pathways in ERG overexpressing PCa tumors." (PMID 30367117, 2019).
tumor (continued). "In three mouse models of PCa, including one with highly recurrent mutations in human PCa (ERG/PTEN), we found distinct contributions of SM-like and fibroblast-like cells to the stroma, yet HH signaling (Gli1nlacZ expression) was restricted to stromal cells, especially near the tumor epithelium." (PMID 27935821, 2017). "Hence, it is likely that ERG protein may be released from tumor cells by necrosis, cell lysis, or micro-vesicle shedding which is then recognized by immune system." (PMID 28191285, 2016). "The fraction of homogeneously ERG positive cancer foci remained largely constant (14–37 %) with increasing tumor focus diameter but the fraction of heterogeneous ERG findings continuously increased with tumor size and reached 39 % in cancer foci larger than 22 mm." (PMID 27530104, 2016). "There is a possibility that ERG AAbs may reflect a change in the tumor stage or treatment." (PMID 28191285, 2016). "In addition, FISH on tissue micro arrays may miss TMPRSS2:ERG positive tumor foci, due to the limited area of analyzed tumor tissue, while qPCR on macro-dissected fresh-frozen tumor tissue could enable a more comprehensive evaluation." (PMID 27798103, 2016). "In such a scenario, the observed ERG signal could be attributed to its expression from tumor cells." (PMID 25889691, 2015). "It is, thus, tempting to speculate that strong SOX9 overexpression inhibits progression through forced differentiation, and that ERG-positive cancer cells consequently need to undergo adaptation steps to adjust SOX9 expression to a level that is compatible with tumor progression." (PMID 26030748, 2015). "Several groups have already shown that circulating tumor cells (CTCs) carrying EWS–FLI1/ERG fusion transcripts may be detected in 6–43 % of the peripheral blood (PB) specimens of ES patients at the time of diagnosis but the prognostic significance of these findings remains disputable." (PMID 25008066, 2014). "The group found that loss of miR-26a led to upregulation of EZH2 in TMPRSS2:ERG negative tumours." (PMID 25496077, 2014). "Immunohistochemical analysis revealed that the tumor cells expressed endothelial cell markers, including CD31, CD34, and ERG." (PMID 40797498, 2025). "Immunohistochemical analysis of the tumor cells showed strong immunoreactivity for vimentin (++), CD31 (++), and ERG (++), with most tumor cells also positive for CD68 (++)." (PMID 40283372, 2025). "The tumor cells exhibited an endothelial cell phenotype with diffuse strong positivity for CD34, CD31, ERG, and FLi-1, and diffuse and strong nuclear reactivity to TFE3." (PMID 39917171, 2025). "Immunohistochemically, the tumor cells in PHA demonstrate positivity for vimentin and the vascular lineage markers, including ERG, CD31, CD34, FLI-1, and factor VIII-related antigen." (PMID 41367857, 2025). "Excisional biopsy from the right thigh lesion showed cohesive tumor cells with epithelioid to spindled morphology in a fibrotic background, vascular involvement, and immunopositivity for vascular markers (CD31, CD34, ERG, and factor VIII)." (PMID 38374236, 2025). "The tumor cells were diffusely CD34, ERG, and focally p63 reactive, while S100 protein, cytokeratin AE1/AE3, Pan-TRK, ALK, smooth muscle actin, and desmin were negative." (PMID 40878874, 2025). "In contrast, metastases with type 2 stroma contained less bone and had more ERG + blood vessels and POSTN + cells, exhibiting higher tumor proliferation and lower PSA levels." (PMID 40841830, 2025). "The study aimed to evaluate the prognostic significance of the PTEN and ERG biomarkers in predicting BCR and tumor progression in PCa patients who underwent radical prostatectomy." (PMID 40863209, 2025). "Remarkably, the small molecule YK-4-279 effectively inhibited ERG- and ETV1-driven transcriptional activity, leading to decreased cell motility and invasion and reduced primary tumor growth and metastasis of fusion-positive PC xenografts." (PMID 40427154, 2025).